WT1 (WT1 transcription factor)
Diseases named in the same sentence as WT1 in open-access papers (continued):
Sharing a sentence is not in itself a finding about the gene and the disease.
cancer (continued). "WT1 expression is important, if not critical, for the growth of some forms of cancer, and its reduced expression by antisense means or by interfering RNA can lead to the induction of differentiation, and to growth inhibition due to cell cycle arrest or cell death." (PMID 17634147, 2007). "Therefore, our findings, regarding intratumoral WT1 nuclear staining of endothelial cells (2 arteries and 1 vein), in otherwise WT1-negative aRCCs, may be reflective of molecular vascular adaptations to ischemia in the RCC microenvironment or the proangiogenic function of WT1 in cancers." (PMID 35453662, 2022). "Although WT1, MUC1, and CA125 are considered tumor antigens and potential targets for cancer immunotherapy, no reports are available on these antigens in ROC." (PMID 25298213, 2014). "Similarly, nuclear staining for WT-1 was specifically observed in MPMs; however, its use in differential diagnosis is likely to be limited because the antigen is often and strongly detected in the cytoplasm of various cancer cells and normal cells (data not shown)." (PMID 22768319, 2012). "In this clinical trial, we evaluated whether the WT1 Trio peptide vaccine enhanced the DTH response and IgG Ab production in patients with recurrent or advanced rare cancers where no standard treatment has been established as the primary endpoints." (PMID 36672344, 2023). "Furthermore, three (WT1, NY-ESO-1 and MG50) of the five cancer-related peptides recognized by T1-116C still did not match the more redundant binding consensus." (PMID 33836029, 2021). "Immunohistochemistry (IHC) was nonspecific and inconsistent (positive for pancytokeratin, PAX8, and CDX2, and negative for CK7, CK20, ER, WT1, calretinin, CD31, CD34, and synaptophysin) and working diagnosis was a putative upper gastrointestinal versus mullerian cancer profile." (PMID 27171493, 2016). "For example, the WT1-specific TCR used in our study was prepared by screening tens of healthy donors and engineered to reduce cross-pairing with endogenous TCRs—such an approach is not possible for patients with rapidly progressing cancers with limited therapeutic intervention time." (PMID 40735486, 2025).
kidney disease (61 papers, 2009 to 2025). "Among the symptoms of kidney disorders associated with WT1 gene pathogenic variants, the most common and widespread symptom is proteinuria occurring from birth." (PMID 40332152, 2025). "WT1 null mice are unable to form kidneys, and WT1 mutations lead to a number of human renal diseases." (PMID 34674704, 2021). "A very important clinical task remains to establish a profound cardiac evaluation of patients presenting WT1 mutations; WT1 has long regarded as a gene implicated solely in kidney disorders." (PMID 34299295, 2021). "Targeted sequencing for 88 known renal disease genes detected a splice-donor site mutation in WT1 intron 9 (NM_024426.6: c.1447 + 4C > T)." (PMID 32838737, 2020). "The WT1 protein has been used as a biomarker of podocyte loss from glomeruli in kidney disease and of the presence of damaged podocytes in urinary sediment." (PMID 28299339, 2017). "This is consistent with previous reports from our laboratory where a low expression of WT-1 in neonatal rats with kidney disease was associated with glomerular changes and reduced nephrogenic markers such as Snail, BMP-7 and E-cadherin." (PMID 27009470, 2016). "Mutations in the Wilm's tumor gene (WT1) can also lead to kidney disease and one isoform of WT1, WT1(+KTS), has been proposed to regulate gene expression post-transcriptionally." (PMID 19652713, 2009). "In addition, in a proportion of children, kidney disease caused by germline WT1 mutations can intrinsically already contribute to organ failure." (PMID 35205701, 2022). "So, the aberrations of WT1 are associated with different pathological variants of kidney diseases." (PMID 35637650, 2022). "Despite the known high risk of kidney disease in patients with WT and constitutional WT1 pathogenic variant, nearly two-thirds of patients had sustained native kidney function, suggesting that nephron-sparing surgery (NSS) should be attempted when possible without compromising oncological risk." (PMID 34608521, 2022). "Besides the renal disorders, our investigation further proposed down-regulated expressions of WT1 and PODXL as desirable indicators for incremental risk and unfavorable prognosis (i.e., renal survival) of IMN." (PMID 31352863, 2019). "Furthermore, with multiplexed scRNA-seq and bulk RNA-seq, we demonstrate the usefulness and necessity of a pooled design to reveal donor iPSC line heterogeneity during macrophage cell differentiation and to model rare WT1 mutation-driven kidney disease with chimeric organoids." (PMID 38729950, 2024). "Wilms tumor-1 (WT-1), essential for podocyte integrity, is detected in uEVs as a marker of glomerular damage in various kidney diseases." (PMID 40807208, 2025). "The five genes COL4A5, COQ8B, NPHP1, PAX2, and WT1 accounted for 66.9% of the monogenetic kidney disease diagnoses." (PMID 39363361, 2024). "Wilms tumor-1 (WT1) protein, a proven histologic biomarker of human podocytopathies, has the potential to diagnose early kidney disease." (PMID 37795410, 2023). "WT1, being an important transcription factor, can bring out remarkable changes in the podocyte phenotype with the onset of kidney disease." (PMID 37795410, 2023). "WT1 has been confirmed to play an important role not only in kidney development but also in the pathogenesis of kidney diseases." (PMID 34226524, 2021). "Uromodulin mRNA in urinary EVs also represented the severity of the progression of renal disease in a sense, and Wilms' tumor 1 (WT1) mRNA reflected glomerular injury." (PMID 34471412, 2021). "Neutrophil gelatinase-associated lipocalin (NGAL), polycystin-1 (PC1), transmembrane protein 2 (TMEM2), and WT-1 (Wilms’ tumor-1) are some exosomal biomarkers that can be applied for the diagnosis of renal diseases." (PMID 34917064, 2021). "Detection of WT1 protein in the urine exosomes, reported by us and others, could be a promising non-invasive approach for the diagnosis of early kidney disease." (PMID 37795410, 2023).
kidney disease (continued). "In 2019, national cohort of children with renal disease from 13 different regions of China were recruited from 2014 to 2018, ADCK4, WT1 and NPHS1 were the top three commonly mutated genes in the SRNS group with mutation rates of 5.7, 5.4, and 2.8%, respectively." (PMID 35755072, 2022). "Based on these results the authors proposed that the determination of WT1 mRNA in podocyte EVs could be an alternative to current methods for WT1 quantification in urine, often masked by albuminuria in renal diseases." (PMID 34064661, 2021). "WT1-related nephropathy is generally ascribed to developmental defects in glomerular podocytes." (PMID 32838737, 2020). "Additionally, a similar approach has been used to detect WT-1-positive cells in kidney disease, and its application in the diagnosis of kidney disease has also been studied." (PMID 32685555, 2020). "Transcription factors in urinary exosomal, such as WT1, have been suggested as a new class of biomarkers for renal diseases and that it may offer insight into cellular regulatory pathways." (PMID 23544132, 2013). "Remarkably, a variant in ZF3 (p.Gln437Lys), which is associated with renal disease but not DSD in XX individuals, showed a low level of interaction with the β-CATENIN protein that is comparable to the WT1-WT." (PMID 32493750, 2020). "In the podocytes of FSGS, elevated expression of microRNA-193a reduced WT1 expression and thereby downregulated target genes of WT1 that are vital to podocyte structure, including PODXL (podocalyxin), NPHS1 (nephrin), VEGFA (VEGFA), etc., eventually leading to kidney disease and proteinuria." (PMID 33921219, 2021).
hematological malignancies (36 papers, 2006 to 2025). "In contrast, much earlier, WT1 was initially implicated as a proto-oncogene for hematological malignancies, leading to the development of the first anti-WT1 immunotherapy applications in this context." (PMID 38929778, 2024). "We are convinced that WT1 is implicated apart from cardiac diseases also in neurological, ophthalmological, as well as hematological disorders." (PMID 34299295, 2021). "WT1 is a nearly universal tumor-associated antigen that is expressed in a broad range of solid and hematological malignancies." (PMID 31546858, 2019). "Although mutations of WT1 were first discovered in hematological malignancies more than a decade ago, the precise roles of WT1 in normal and malignant hematopoiesis remain elusive." (PMID 21917154, 2011). "Notably, both somatic mutations and the aberrant overexpression of WT1 have been recurrently observed in hematologic malignancies, frequently aligning with specific molecular subtypes and clinical features." (PMID 40507300, 2025). "WT1 expression and multidrug resistance are associated in some hematological malignancies, suggesting that WT1 may be a marker for chemoresistance." (PMID 17137506, 2006). "Yet, WT1 presents an ideal target for developing autologous epitope-specific T-cell therapies and monitoring disease progression in hematologic malignancies." (PMID 40847198, 2025). "Immunotherapy targeted against WT1 in various hematological malignancies and solid cancers has induced immunological and clinical responses in preclinical studies and clinical trials for solid tumors and hematologic malignancies." (PMID 38190392, 2024). "Wilms’ tumor gene 1 (WT1) is expressed in various types of solid tumors and hematological malignancies and plays important roles in oncogenesis." (PMID 39509060, 2024). "The transcription factor Wilms tumor one (WT1) is highly expressed in malignant cells of patients with hematological malignancies, with a considerable percentage of patients harboring deactivating mutations in this gene." (PMID 37444601, 2023). "Wilms Tumor 1 (WT1) is a zinc-finger transcription factor overexpressed in various hematological disorders." (PMID 37803464, 2023). "These limitations drastically limit the choice of antigens: the majority of TCR-T therapies use the NY-ESO-1 and WT-1 targets against solid and hematological malignancies, respectively." (PMID 36900382, 2023). "Wilms tumor protein-1 (WT1) is an attractive target for adoptive T-cell therapy due to its expression in solid tumors and hematologic malignancies." (PMID 30678050, 2019). "Nevertheless, WT1 has been identified as a target antigen of other solid tumors and of hematological malignancies, such as AML where it is expressed at high level." (PMID 31546858, 2019). "Multiple reports have shown that WT1 mutations are a recurrent event in AML and MDS, yet it is not well understood how WT1 mutations contribute to the development of hematologic malignancies." (PMID 30450160, 2018). "WT1 is over-expressed in many malignant hematologic diseases, with this gene expression already being used in the monitoring of AML patients and is also being investigated for use in immunotherapy." (PMID 29662637, 2018). "Investigators at Memorial Sloan Kettering Cancer Centre, New York, have pioneered the use of in vitro expanded T cells specific for peptide epitopes of the Wilms Tumour 1 (WT-1) protein in patients with WT-1+ hematologic malignancies." (PMID 28635677, 2017). "A clinical trial of a WT1 peptide allogeneic dendritic cell vaccine is being conducted at the NCI for children and adults with WT1-expressing hematologic malignancies and persistent or relapsed disease after SCT (NCT00608166)." (PMID 23847759, 2013). "WT1-specific T cells have been shown to correlate with relapse-free survival in patients with hematologic malignancies after allogeneic SCT." (PMID 23847759, 2013).
hematological malignancies (continued). "These HLA class I types are frequently found in humans, and both our research and that of others have reported a series of successful clinical studies using these WT1 peptide-based vaccine therapies for patients with solid tumors and hematological malignancies." (PMID 39509060, 2024). "The role of WT-1 in hematologic malignancies has not been clearly understood." (PMID 33747867, 2021). "A detailed understanding of the role of WT1 in malignant hematologic diseases may improve and consolidate its utilization in the clinical setting." (PMID 29662637, 2018). "The functional role of WT1 mutations in hematologic malignancies appears to be complex and is not yet fully elucidated." (PMID 30450160, 2018). "However, regardless of the presence or absence of these mutations, our results indicate that the expression of WT1 from the nonmutated second allele is high in the majority of hematological malignancies, showing a relatively consistent isoform pattern." (PMID 37444601, 2023). "Wilms’ tumor 1 (WT1) is overexpressed in a variety of solid tumor types and hematologic malignancies." (PMID 36138335, 2023). "Wilms tumor 1 (WT1) is a tumor suppressor gene and a regulator of apoptosis, which is expressed in various types of solid tumors and several hematologic malignancies." (PMID 22769020, 2012).
adenocarcinoma (21 papers, 2008 to 2026). A common cancer characterized by the presence of malignant glandular cells. "Biomarkers that are most commonly used for this purpose include mesothelial (calretinin, D2-40, WT1 and cytokeratin 5/6), epithelial (Claudin 4), and adenocarcinoma markers (Ber-EP4, TTF-1, CEA, MOC31, Napsin A)." (PMID 36292206, 2022). "Thoracentesis studies revealed an exudative pleural effusion positive for malignant cells showing adenocarcinoma, which had an immunopathologic profile (WT-1 and PAX8) favoring an adenocarcinoma of kidney origin." (PMID 33815993, 2021). "In the clinical setting, immunohistochemistry was not employed to select WT1 and MUC1 peptides because previous studies reported the overexpression of WT1 and MUC1 in adenocarcinoma of gastrointestinal cancers." (PMID 39737308, 2024). "In doubtful cases, IHC stains can confirm the mesothelial origin; calretinin, WT-1, HBME-1, and D2-40 are positive in mesothelial cells and usually negative in adenocarcinoma, while MOC-31, Ber-EP4, B72.3 (BRST-3), and CEA are positive in adenocarcinoma and usually negative in mesothelial cells." (PMID 37359022, 2023).
infection (20 papers, 2013 to 2025). The state of being infected such as from the introduction of a foreign agent such as serum, vaccine, antigenic substance or organism. "The immunoblot confirmed WT1 knockdown by stable infection at the protein level with an anti-WT1 antibody." (PMID 40613901, 2025). "WT1 upregulation was confirmed in primary endothelial cells and a second cell line, by performing time course infections followed by WT1 protein analyses in primary HUVEC and HUVEC ORFE4 cells, a HUVEC line immortalized with adenovirus E4." (PMID 38190392, 2024). "We show that major oncogenic isoforms of WT1 are overexpressed in primary KS tissue and observed WT1 upregulation upon de novo infection of endothelial cells with KSHV." (PMID 38190392, 2024). "In vitro infection usually occurred in less than 40% of the total cellular population, so levels of WT1 seen by Western blot likely underestimate upregulation in the infected cells." (PMID 38190392, 2024). "Specifically, our analysis revealed the role of enhancer mediated transcriptional regulation after SARS-CoV-2 infection in manipulating WT1 activity, cell-to-cell infection, MAPK signaling, Wnt signaling and pro-inflammatory cytokines." (PMID 37561814, 2023). "Infection of iPSCs harboring a doxycycline (DOX)-inducible Cas9 protein with lentiviruses driving expression of a WT1-specific guide RNA (gRNA1)." (PMID 36120564, 2022). "Due to AML relapse, the patient had to stop vaccination therapy and died due to infection three months after the first WT1-based treatment injection." (PMID 35476127, 2022). "Overall, these results suggest that Wt1-5 infection of Reh cells can induce direct and indirect cell death mechanisms." (PMID 32722005, 2020). "It sounds plausible to suggest that the Wt1-5 infection can contribute to Bax activation through the decrease in the Bax/Bcl-2 complex number in the mitochondrial membrane." (PMID 32722005, 2020). "Early apoptotic signals induced by Wt1-5 infection on Reh cells were assessed by detecting phosphatidylserine exposure in the outer cell membrane." (PMID 32722005, 2020). "The results indicated that Wt1-5 infection resulted in DNA fragmentation that was compatible with an apoptotic DNA fragmentation pattern in comparison to agarose electrophoretic patterns for DNA from non-infected cells and H2O2-treated cells used as a control." (PMID 32722005, 2020). "This corresponded with activation of KEGG pathways representing responses to inflammation, infection, and injury in WT1-intermediate cells." (PMID 31615982, 2019). "We also tested WT1 knockdown after shRNA infection of K562 affected the expression of each isoform." (PMID 40613901, 2025). "In addition, only one INHRsample showed both WT1 (wild type) and mutant bands, suggesting heteroresistanceor mixed infection." (PMID 39292021, 2024). "The novel finding of WT1’s impact on increased cell adhesion warrants further investigation and may be a significant factor in facilitating cell-to-cell infection of SARS-CoV-2." (PMID 37561814, 2023). "The LDH activity present in the 700 g supernatant fraction suggests that cell membrane permeability is significantly and selectively affected by Wt1-5 infection of Reh cells in an MOI-dependent manner, while the cell membrane permeability of PBMCs was not affected." (PMID 32722005, 2020). "Furthermore, the cytotoxic effects induced by Wt1-5 infection are compatible with an apoptosis-induced cell death which is dependent on the MOI and post-infection times." (PMID 32722005, 2020). "In addition, Wt1-5 infection of Reh cells induced cell mortality as evidenced by a decreased cell viability that was nearly proportional to the MOI values used." (PMID 32722005, 2020).
infection (continued). "No significant changes in the levels of expression of podocyte marker genes (WT1, PODXL, NPHS1, NPHS2, and MAFB) or for tubular marker genes (SLC3A1 and SLC16A1) were found after infection comparing WT and ACE2 KO kidney organoids." (PMID 35561674, 2022). "Six inducing factors, Sry, Sox9, SF1, WT1, GATA4, and Dmrt1, were respectively transduced into mES cells by lentiviral infection according to the experimental design." (PMID 30850007, 2019). "Age > 60, a clinical factor associated with the TLT subtype, was associated with 57 upregulated genes, including BCR signaling genes, IL6 (related to infection), and IL21R (different from TLT vs. ME), and 141 downregulated genes including EPCAM, AR, WT1, and CD28." (PMID 39866884, 2025). "The effect of KSHV infection on binding of ESK-1 antibodies, which recognize WT1 peptides presented on HLA-A0201, was tested by transducing HuARLT-1 with HLA-A0201, followed by KSHV infection which resulted in infection of approximately 30% of cells measured by GFP expression." (PMID 38190392, 2024). "It appears to be that the very low expression of cell surface HSPs in PBMCs was not enough to make possible the infection by Wt1-5." (PMID 32722005, 2020). "Finally, CMV replication in fibroblasts stimulates WT1 expression, which competes antagonistically for EGR1 targets, including EGFR, and indicates another mechanism by which the virus antagonizes EGFR/EGR1 signaling for productive infection." (PMID 31725811, 2019). "mES cells with lentiviral transduction of all the six factors, Sry, Sox9, SF1, WT1, GATA4, and Dmrt1 (mES+Trans) had a relatively less growth rate as compared to those without infection (group mES+MEF and mES+TM4)." (PMID 30850007, 2019).